ATF5 (activating transcription factor 5)
Diseases named in the same sentence as ATF5 in open-access papers (continued):
Sharing a sentence is not in itself a finding about the gene and the disease.
brain tumors (6 papers, 2010 to 2025). "Findings such as the fact that ATF5 suppresses the differentiation of neuroprogenitor cells and promotes their proliferation raised the question of its potential role in brain tumors." (PMID 36831248, 2023). "These and other over-expression findings thus have supported the idea of a role for ATF5 in brain tumor malignancy." (PMID 36831248, 2023). "ATF5 mRNA levels have also been quantified in brain tumors by several groups." (PMID 36831248, 2023).
pancreatic cancers (6 papers, 2014 to 2025). "While this is significant, the studies were performed with a single cell line and therefore more studies need to be conducted to establish the association between ATF5 activity and clinical presentations of pancreatic cancer." (PMID 29137451, 2017). "ATF5 is highly expressed in pancreatic cancer tissues compared with adjacent normal pancreatic tissues and localized in the nuclei of collagen-rich and stiff pancreatic cancer cells." (PMID 40124511, 2025). "Especially, we revealed that F-actin is necessary for ATF5-dependent responses in pancreatic cancer cells, whereas the phosphorylation of the myosin regulatory right chain is not critical." (PMID 40124511, 2025). "We confirmed that ATF5 levels in pancreatic cancer tissues were significantly higher than those in corresponding adjacent normal tissues." (PMID 40124511, 2025). "ATF5 expression has been confirmed in pancreatic cancer cell lines and significant upregulation is seen in primary tumors relative to normal pancreatic tissue, suggesting a role for ATF5 in the development of pancreatic cancer." (PMID 29137451, 2017). "Our previous studies demonstrated that ATF5 is highly expressed in epithelial ovarian carcinomas and human pancreatic carcinomas, compared with healthy ovarian and pancreatic tissues." (PMID 25120656, 2014). "At the same time, ATF5 prevents the growth of pancreatic cancer cells by promoting YAP1 expression." (PMID 40124511, 2025). "Indeed, in mouse pancreatic cancer tissues, ATF5 is more highly localized to the nucleus in stiff than in soft tissues." (PMID 40124511, 2025). "Furthermore, we found that ATF5 was highly localized in the nuclei of collagen-rich pancreatic cancer tissues than in those of collagen-poor pancreatic cancer tissues." (PMID 40124511, 2025). "However, although specific small molecules capable of inhibiting ATF5 activity are yet to be reported, these may act as potent drugs that may be utilized to counter stiff cancers, including refractory pancreatic cancers." (PMID 40124511, 2025). "Therefore, the simultaneous inhibition of ATF5 and YAP1 may be an effective therapy for pancreatic cancer." (PMID 40124511, 2025). "Collectively, these results suggest that YAP1 binds to KLF5 and promotes the growth of pancreatic cancer cells, independent of TEAD and TAZ, and also indicate that ATF5 enhances the growth of pancreatic cancer cells by suppressing EGR1 expression." (PMID 40124511, 2025). "We further analyzed the expression of ATF5 and EGR1 in mouse pancreatic cancer tissues treated with or without AM80, which reduces tissue stiffness by increasing the number of meflin-positive cancer-restraining CAFs." (PMID 40124511, 2025).
HCMV infection (5 papers, 2014 to 2025). "Therefore, it is reasonable to suppose that the cell survival promoting caused by HCMV infection may be related with ATF5." (PMID 28473657, 2017). "It is hypothesized that anti-apoptosis of HCMV infection may be associated with ATF5 pathways." (PMID 25120656, 2014). "ATF5 mRNA was upregulated 12 h following HCMV infection and continued to increase until 48 h following infection." (PMID 25120656, 2014). "Cell viability following ATF5 interference in U87 cells was marginally increased following HCMV infection when compared with siATF5 U87 cells." (PMID 25120656, 2014). "In the present study, it was found that HCMV infection in U87 cells regulated the expression of ATF5." (PMID 25120656, 2014). "The results of the present study demonstrated that HCMV infection in U87 cells promotes cell proliferation and upregulates the expression of ATF5." (PMID 25120656, 2014). "Loss of ATF5 function was achieved using a dominant-negative form of ATF5 in U87 cells, whereby cells appeared to grow marginally following HCMV infection when compared with the control." (PMID 25120656, 2014). "HCMV infection promotes the expression of ATF5 and elevates the Bcl-2 to BAX ratio and enhances anti-apoptosis in U87 cells." (PMID 25120656, 2014). "The results of the current study revealed that the ATF5 signaling pathway is involved in the anti-apoptotic effects that are induced by HCMV infection in U87 cells." (PMID 25120656, 2014). "Interestingly, HCMV infection sustains high ATF5 levels by downregulating a microRNA, miR-134-5p, which negatively regulates ATF5 transcription." (PMID 40622847, 2025). "In addition, when interfering with ATF5 in U87 cells, the anti-apoptotic ability was decreased following HCMV infection." (PMID 25120656, 2014). "Furthermore, following interference with ATF5 in U87 cells, the anti-apoptotic ability was decreased following HCMV infection." (PMID 25120656, 2014). "We showed that HCMV infection or IE expression increase ATF5 expression after serum deprivation but not in a very significantly level." (PMID 28473657, 2017).
Obesity (5 papers, 2017 to 2024). Accumulation of substantial excess body fat. "This study found ATF5 expression to be associated with the obesity-related phenotype, suggesting its role in promoting adipocyte differentiation." (PMID 39273102, 2024). "Intriguingly, ATF5 supports intestinal barrier function by promoting a satiety response that prevents obesity and associated hyperglycemia." (PMID 36516750, 2022). "Given the relationships between obesity and the integrity of the intestinal barrier, we were motivated to explore the relationships between ATF5 and regulation of weight gain and feeding behavior." (PMID 36516750, 2022). "By transcriptionally controlling the expression of the gut-derived hormone Cck, ATF5 is able to positively regulate serum leptin levels, thus stimulating satiety and preventing obesity." (PMID 36516750, 2022). "Overall, these findings give evidence for ATF5-mediated adipogenesis and even suggest a potential role for ATF5 in obesity." (PMID 29137451, 2017). "Moreover, obesity elicited a higher binding between POLG and ATF5 protein, suggesting that the ATF5‐POLG complex might drive mutated mtDNA replication." (PMID 38499990, 2024).
Hyperglycemia (4 papers, 2021 to 2023). An increased concentration of glucose in the blood. "The regulation of appetite by ATF5 ultimately promotes intestinal barrier function by preventing alterations to glucose metabolism caused by hyperglycemia." (PMID 36516750, 2022). "As a part of this defense mechanism, ATF5 promotes intestinal barrier integrity through the stimulation of the satiety response and the prevention of hyperglycemia." (PMID 36516750, 2022). "While we show that ATF5 promotes intestinal barrier function by regulating the satiety response and preventing hyperglycemia, we are still unclear of the exact relationship at a mechanistic level." (PMID 36516750, 2022). "Overall, ATF5 promoted tubulointerstitial injury under long-term hyperglycemia by regulating the excessive UPRmt pathway, although it might exert a protective effect in the very early stage." (PMID 37095454, 2023).
lymphoma (4 papers, 2016 to 2026). A malignant (clonal) proliferation of B- lymphocytes or T- lymphocytes which involves the lymph nodes, bone marrow and/or extranodal sites. "ATF5 for instance was found overexpressed in lymphoma and was recently associated with transformation to aggressive form of follicular lymphomas." (PMID 29129929, 2017). "Taken together, these results suggested that ATF5 induces ascorbate resistance in lymphoma cells by activating transcription factors." (PMID 27590508, 2016). "ATF5, a MYC-regulated transcription factor overexpressed in these lymphomas, induces SLC7A11 expression." (PMID 41998301, 2026).
Anxiety (3 papers, 2017 to 2024). Intense feelings of nervousness, tension, or panic often arise in response to interpersonal stresses. "ATF5-deficient (ATF5−/−) mice exhibit behavioural abnormalities, including reduced social interaction and behavioural flexibility, increased anxiety-like behaviours, and hyperactivity in novel environments." (PMID 33790322, 2021). "We previously reported that ATF5-deficient (ATF5−/−) mice exhibited behavioural abnormalities, including abnormal social interactions, reduced behavioural flexibility, increased anxiety-like behaviours, and hyperactivity in novel environments." (PMID 33790322, 2021). "Taken together, these results suggest that ATF5 deficiency enhances anxiety-like behavior." (PMID 28744205, 2017). "Increased stereotypic activity in ATF5-/- mice may be associated with stress-coping behavior, while ATF5-/- mice also exhibited anxiety-like behavior." (PMID 28744205, 2017). "We previously demonstrated that ATF5−/− mice exhibited abnormal behaviours including hyperactivity in novel environments, increased anxiety-like behaviour, reduced social interaction, and reduced behaviour flexibility." (PMID 33790322, 2021). "In summary, ATF5-/- mice exhibited behavioral abnormalities including hyperactivity in novel environments, increased anxiety-like behavior, reduced social interaction, higher pain sensitivity, and reduced behavior flexibility." (PMID 28744205, 2017). "We examined locomotor activity and anxiety-like behavior of ATF5-/- mice using the light/dark transition test, the open field test, and the elevated plus maze test." (PMID 28744205, 2017). "The time spent in the light chamber was lower than for ATF5+/+ mice, suggesting increased anxiety-like behavior." (PMID 28744205, 2017). "Our results demonstrated that ATF5-/- mice exhibited abnormal locomotor activity in novel environments, abnormal anxiety-like behavior, reduced social interaction behavior, higher pain sensitivity, and reduced behavioral flexibility." (PMID 28744205, 2017). "The anxiety-like behavior of ATF5-/- mice may therefore be due to changes in levels of dopamine and its metabolites in the BLA." (PMID 28744205, 2017). "In this study, ATF5-/- mice demonstrated behavioral abnormalities including hyperactivity in novel environments, abnormal anxiety-like behavior, reduced social interaction, higher pain sensitivity, disturbed circadian rhythms, and reduced behavioral flexibility." (PMID 28744205, 2017). "ATF5-/- mice spent less time in the center area in the open field test and in the center area in the elevated plus maze test, suggesting increased anxiety-like behavior." (PMID 28744205, 2017). "Moreover, ATF5-/- mice demonstrated abnormal anxiety-like behavior in the light/dark transition test." (PMID 28744205, 2017). "Various studies have identified detrimental phenotypes in knockout mice; for example, ATF5-KO mice may have abnormal cortical development and abnormal behaviors, such as anxiety, and SIRT1-KO mice may have abnormal bone development, autoimmune disease, and other problems." (PMID 38278820, 2024). "However, in ATF5-/- mice, the number of transitions was greater, which might suggest reduced anxiety-like behavior in ATF5-/- mice or might reflect hyperactivity." (PMID 28744205, 2017).
chronic lymphocytic leukemia (3 papers, 2010 to 2023). "In another study, expression profiling in chronic lymphocytic leukemia (CLL) patients of known clinical outcome identified ATF5 as a gene whose significant over-expression correlates with poor patient outcome." (PMID 21311102, 2010). "Increased ATF5 expression has been reported in aggressive chronic lymphocytic leukemia, follicular lymphoma, and childhood acute lymphoblastic leukemia, implying potential involvement of ATF5 in the tumorigenesis and progression of these hematopoietic malignancies." (PMID 38223508, 2023).
viral infection (3 papers, 2016 to 2025). "To interfere with ATF5 function, we previously designed and employed a d/n-ATF5 construct delivered by viral infection, transfection or as an inducible transgene." (PMID 26863637, 2016). "Moreover, ATF5 translational upregulation was also shown to occur during viral infection of murine cells with the betacoronavirus mouse hepatitis virus." (PMID 40622847, 2025).
acute lymphoblastic leukemia (2 papers, 2017 to 2021). Leukemia with an acute onset, characterized by the presence of lymphoblasts in the bone marrow and the peripheral blood. "Moreover, ATF5 gene polymorphisms that appear to enhance activity at the ASNS promoter are linked to asparaginase treatment resistance in childhood acute lymphoblastic leukemia." (PMID 34065488, 2021).
anxiety disorder (2 papers, 2017 to 2021). A category of psychiatric disorders which are characterized by anxious feelings or fear often accompanied by physical symptoms associated with anxiety. "ATF5-/- mice may provide a useful model for the study of psychiatric disorder pathology, including ASD, anxiety disorder, hyperactivity disorder, and so on." (PMID 28744205, 2017). "Therefore, we surmise that ATF5−/− mice may provide a useful model for the study of psychiatric disorder pathology, including ASD, anxiety disorder, hyperactivity disorder, and so on." (PMID 33790322, 2021).
bladder cancer (2 papers, 2021 to 2025). "In this study, we were able to confirm the findings of previous studies which indicated that ATF5 was highly expressed in cancer tissues, such as those of pancreas, lung, breast, and bladder cancers, which are stiffer than the corresponding normal tissues." (PMID 40124511, 2025). "Subsequently, the tumor sphere formation test was carried out to investigate the role of ATF5 in self renewal of spherogenic bladder cancer cells." (PMID 34895217, 2021). "This study revealed that ATF5 facilitates the formation of tumor sphere, promotes tumorigenicity and stimulates the Wnt/β-catenin pathway in bladder cancer." (PMID 34895217, 2021). "Altogether, this result showed that ATF5 promoted tumorigenic capability of bladder cancer cells by directly binding and promoting DVL1 to stimulate the Wnt/β-catenin pathway." (PMID 34895217, 2021). "Overexpressing ATF5 significantly enhanced, whereas silencing ATF5 inhibited, the capability of tumor sphere formation in bladder cancer cells." (PMID 34895217, 2021). "Therefore, ECM stiffening and ATF5 show potential as potent therapeutic targets in stiff tumors, such as pancreatic, lung, breast, and bladder cancers." (PMID 40124511, 2025). "Finally, qRT-PCR and WB analyses were performed to check if the Wnt/ATF5/DVL1 axis in bladder cancer cells is of clinical significant." (PMID 34895217, 2021). "Moreover, ATF5 upregulation enhanced DVL1 promoter-driven luciferase activity and DVL1 expression in bladder cancer cells, while ATF5 knockdown exhibited the opposite effects." (PMID 34895217, 2021). "Furthermore, we found that overexpressions of ATF5 in bladder cancer cells promoted the formation of tumor sphere, which was correlated with the relapse-free survival of BLCA patients." (PMID 34895217, 2021). "Our results indicated that ATF5 up-regulation could promote the stemness of bladder cancer cells." (PMID 34895217, 2021). "Moreover, qRT-PCR and WB showed that the expression levels of stemness-associated biomarkers, such as OCT4, ABCG2 and SOX2 were markedly elevated in ATF5-overexpressed SW780 and UM-UC-3 cells, whereas reduced in ATF5-silenced bladder cancer cells." (PMID 34895217, 2021). "In summary, these results showed that ATF5 overexpression in BLCA was positively related to DVL1 expression, which in turn stimulated Wnt/β-catenin pathway to promote tumorigenic capability of bladder cancer cell." (PMID 34895217, 2021). "Notably, bladder cancer with ATF5 amplification was found to be a predictor of worse survival outcomes than those without ATF5 amplification (P = 0.014)." (PMID 34895217, 2021).
brain cancer (2 papers, 2017 to 2023). A primary or metastatic malignant neoplasm affecting the brain. "Our interest in ATF5 and its potential role in brain cancers first arose from studies to identify genes regulated by nerve growth factor (NGF) in the context of neuronal differentiation." (PMID 36831248, 2023). "In thisstudy, the authors develop a biomimetic lipoprotein nanoparticle for the efficientdelivery of ATF5 siRNA in Ras-activated brain cancer cells, where thenanoparticle is internalized by macropinocytosis in a Ras-dependentmanner." (PMID 28489075, 2017). "Overall, by applying this nanoplatform, we efficiently deliver ATF5 siRNA toRas-activated brain cancer cells, where the nanoparticle is uptaken bymacropinocytosis in a Ras-dependent mechanism." (PMID 28489075, 2017). "The studies cited above identify ATF5 as a potential target in GBM and possibly other brain cancers." (PMID 36831248, 2023). "While this review focuses on ATF5, CEBPB and CEBPD in the context of brain cancers, it is important to consider, as we briefly do here, the roles of these transcription factors in other types of cancers and how the targeted peptide drugs discussed here may be used to treat these as well." (PMID 36831248, 2023).
cardiac hypertrophy (2 papers, 2020 to 2024). "Our study demonstrates that CTRP3 activates UPRmt via the SIRT1/ATF5 axis under pathological myocardial hypertrophy, thus attenuating mitochondrial dysfunction and oxidative stress injury." (PMID 38278820, 2024). "In conclusion, this study shows that CTRP3 activated UPRmt through the SIRT1/ATF5 axis and alleviated mitochondrial dysfunction and oxidative stress injury under pathological cardiac hypertrophy." (PMID 38278820, 2024). "Here, we identified a novel mechanism of CTRP3 against cardiac hypertrophy by activating UPRmt via the SIRT1/ATF5 axis." (PMID 38278820, 2024). "Collectively, the present study provides the first evidence that PGC-1 and ATF5 can form a signaling axis to partly activate UPRmt that mediates the cardioprotective role of THC in pathological cardiac hypertrophy." (PMID 33425220, 2020). "PGC-1α/ATF5/UPRmt also mediates the protective role of THC against pathological cardiac hypertrophy and oxidative stress induced by pressure overload in vivo and by PE treatment in vitro." (PMID 33425220, 2020). "Furthermore, PGC-1α/ATF5/UPRmt mediates the protective role of THC in TAC-induced cardiac hypertrophy and oxidative stress." (PMID 33425220, 2020). "This study primarily verified that the newfound PGC-1α/ATF5 axis can partly activate UPRmt and mediate the protective role of THC against pathological cardiac hypertrophy and oxidative stress induced by pressure overload." (PMID 33425220, 2020).
COVID-19 (2 papers, 2021 to 2024). A disease caused by infection with severe acute respiratory syndrome coronavirus 2. "We prioritized 4 out of 5 microglia PFC TFs (IRF8, ATF5, SPI1, TAL1) based on the upregulation in their activity in patients with COVID-19 (Z > 2.5, P < 0.05 and FDR within cell type < 0.05)." (PMID 34281603, 2021).
esophageal cancer (2 papers, 2021). A primary or metastatic malignant neoplasm involving the esophagus. "The TCGA RNA-seq database for esophageal cancer patients showed higher expression of ATF5, BATF, and FOSL1 in cancer tissues, which is consistent with the finding of greater expression of these genes in KYSE-30 cells." (PMID 34722266, 2021).
leukemia (2 papers, 2017 to 2021). A malignant (clonal) hematologic disorder, involving hematopoietic stem cells and characterized by the presence of primitive or atypical myeloid or lymphoid cells in the bone marrow and the blood. "Several studies have reported the significance of ATF5 activity to clinical outcomes in leukemia patients." (PMID 29137451, 2017). "The importance of ATF5 in the development of leukemia first became evident during analysis of its role in the survival of myeloid progenitor cells." (PMID 29137451, 2017).